OR1I1 (olfactory receptor family 1 subfamily I member 1)
Description:
Odorant receptor.
Synonyms: OR19-20; OR1I1P; OR1I1Q
Tractability: Antibody: UniProt places it where antibodies can reach, with medium confidence; UniProt predicts a signal peptide or a membrane-spanning region; its Gene Ontology location is reachable by antibodies, with medium confidence.
Gene: Protein-coding gene on chromosome 19 (15,082,211 to 15,092,970, forward strand). Ensembl gene ENSG00000094661.
Subcellular location: Cell membrane
Pathways (Reactome):
Sensory Perception: Expression and translocation of olfactory receptors
Gene Ontology:
Molecular function: olfactory receptor activity; G protein-coupled receptor activity
Biological process: signal transduction; detection of chemical stimulus involved in sensory perception of smell; G protein-coupled receptor signaling pathway
Cellular component: plasma membrane; membrane
Genetic constraint (gnomAD): Missense variants: 418 observed, 426.42 expected, observed/expected ratio (o/e) 0.98, 90% interval 0.9 to 1.06. Synonymous variants: 156 observed, 177.85 expected, observed/expected ratio (o/e) 0.88, 90% interval 0.77 to 1.
Homologues: Orthologues: macaque OR1I1 (89% identical), pig OR1I1 (68% identical), dog OR1I1 (68% identical), mouse Or1i2 (67% identical), rat Or1i2 (66% identical), guinea pig OR1I1 (65% identical), rabbit OR1I1 (64% identical). Paralogues in human: OR1F1 (48% identical), OR1G1 (48% identical), OR1N1 (48% identical), OR1N2 (47% identical), OR7D4 (47% identical), OR1M1 (47% identical), OR7A17 (47% identical), OR1J4 (46% identical), OR1J2 (46% identical), OR7C2 (46% identical), OR7E24 (46% identical), OR1E1 (46% identical), and 116 more.